AURKB (aurora kinase B)
Diseases named in the same sentence as AURKB in open-access papers (continued):
Sharing a sentence is not in itself a finding about the gene and the disease.
cancer (continued). "Aurora kinase B (AURKB) is a subunit of chromosomal passenger complex (CPC), involved in the segregation of chromatids, cytokinesis and modification of histones and has been overexpressed in different types of cancers encompassing prostate, thyroid and brain." (PMID 31521144, 2019). "In HPV-positive HNSC, the expression of TAGLN is significantly decreased, while AURKB is strongly upregulated, suggesting that HPV might be responsible for gene alterations that are important in cancer development in general." (PMID 30918060, 2019). "AURKB, in combination with EGFR knockdown, have shown enhanced therapeutic effect by inhibiting PC3 cell proliferation and inducing apoptosis in vitro, whereas androgen-dependent cancer cells, LNCaP, remain unaffected by the endogenous expression levels." (PMID 31581661, 2019). "For example, in the seven cancer types (BLCA, ESCA, HNSC, KIRC, LIHC, STAD and UCEC) with both grade phenotype information and normal control samples, expression of AURKB, BUB1, FOXM1, HMMR, MYBL2, and PLK1 follows the pattern in five cancer types (BLCA, HNSC, KIRC, LIHC, and UCEC)." (PMID 28427185, 2017). "The FOXM1 transcription factor is a proto-oncogene involved in cell cycle progression, cell proliferation, tumorigenesis and cancer progression, and many of its target genes (> 20) were downregulated in paclitaxel-residual MDA-MB-231 cells including AURKB, CCNB1, PLK1, PLK2, and the kinesin KIF20A." (PMID 28187446, 2017). "In all three cancer cell lines, Western blot analysis showed a decrease of p-H3, cyclin B1, and AURKB, 72 hr after LOX knockdown, but not with BAPN treatment." (PMID 27296552, 2016). "This suggests that Aurora kinase family members, particularly AURKB, may play a role in mediating CIN in advanced BRAF mutant/MSS cancers." (PMID 23110075, 2012). "Moreover, similar to AURKB, MAD2L2 was highly expressed in pan-cancer." (PMID 38515112, 2024). "In addition, AMG900 treatment in cancer cells suppresses most of the genes in the TPX2/AURKB subnetwork but not in the COL1A2 subnetwork." (PMID 35332150, 2022). "Based on current researches and observations, MLN8237 (Alisertib), one of AURKA selective inhibitor, and the AURKB selective inhibitor AZD1152 are successfully attracted researchers attention and are undergoing III clinical trials due to their potential dominant suppression for cancer treatment." (PMID 28147341, 2017). "Importantly, TRAF6 was found to be autoubiquitinated, which is consistent with its activation, during mitotic progression at the same time as AURKB is active, in agreement with our hypothesis that active TRAF6 has impact on AURKB to regulate proliferation of cancer cells." (PMID 35853811, 2022). "However, our results showed that centrinone, the most selective inhibitor for PLK4, did not induce polyploidy of the cancer cells, which raises the hypothesis that the major factor responsible for polyploidy is inhibition of AURKB rather than PLK4." (PMID 31035676, 2019). "Also, mutations in mitotic checkpoint genes themselves are not found responsible for abnormal checkpoint in cancer cells and infrequently reported for core SAC proteins like Cdc20, Bub3, and Mad2, and SAC-associated proteins like Borealin, Zwint, Hec1, and Aurora kinase B." (PMID 25999914, 2015). "Gene expression analysis showed that clonogenic side population cells in cancers express genes involved in the cell cycle and mitosis (e.g., SKA1, CCNB1, CDC25C, CDC2, BIRC5, CENPE, AURKB, KIFs, TOP2A, ASPM) more strongly than non-side population cells." (PMID 23962337, 2013).
cancer (continued). "We observed a significant correlation between the percentage of samples where a kinase is regulated in cancer and noncancer conditions (Pearson's r = 0.78, P‐value = 2.2e‐16), with AKT1 and the cell‐cycle kinases CDK1/2 and AURKB being highly regulated in both sets of conditions." (PMID 36688815, 2023). "We show that while exosome-induced cancer cell motility requires neither centrosomes nor the MT network, it is critically dependent on CEP192, the CEP192 interacting kinase PLK4, and the Chromosomal Passenger Complex (CPC) protein Aurora Kinase B (AURKB)." (PMID 31142743, 2019).
tumor (241 papers, 2004 to 2026). "An aberrant expression of AURKB in tumors causes chromosomal instability and aneuploidy, leading to tumorigenesis, tumor migration, and invasion." (PMID 39927464, 2025). "Zebrafish and cell-based systems provide direct evidence that loss of EWSR1 promotes LOH and aneuploidy via AURKB -dependent mitotic defects, while human tumor profiles confirm selection for conditions that allow CIN." (PMID 41301081, 2025). "Accumulating evidence indicates that AURKB is associated with tumor development, invasion, metastasis, poor prognosis, and drug resistance in various malignancies." (PMID 38515112, 2024). "Elevated expression of AURKB is strongly associated with an unfavourable prognosis in various types of tumours." (PMID 38898693, 2024). "The study further analysed associations between AURKB and factors such as prognosis, pathological stage, biological function, immune infiltration, tumour mutational burden (TMB) and microsatellite instability (MSI)." (PMID 38898693, 2024). "AURKB is a gene encoding mitotic Aurora Kinase B that is overexpressed in some tumor cells, making it an interesting therapeutic target." (PMID 37631072, 2023). "AURKB has been implicated in the inactivation of the tumor suppressor by phosphorylation of Rb at Ser780." (PMID 36292957, 2022). "In HCC, overexpression of AURKA and AURKB is associated with tumor aggressiveness, an unfavorable prognosis, and poorer outcomes, and their co-expression is an independent predictor of PFS and OS." (PMID 35062934, 2022). "Deregulation of AURKB is observed in several tumors and its overexpression is frequently linked to tumor cell invasion, metastasis and drug resistance." (PMID 33915740, 2021). "Proteins encoded by CDK1, BUB1 and AURKB belong to the serine/threonine kinases family, and overexpression of them has been detected involved in various tumors prognosis via regulating tumor cell cycle." (PMID 32411535, 2020). "It has been proposed that AURKB overexpression causes defects in chromosome segregation, aneuploidy and tumor development." (PMID 31521144, 2019). "In particular mutations in ERBB2, PTPRD, PTPRT, AURKB correlated with at least one of the clinical-pathological parameters under analysis such as node status (N), stage, tumor size (T) and/or presence of metastasis (M1)." (PMID 29844865, 2018). "Univariate analysis revealed a statistically significant association between the number of Aurora kinase B positive tumor cells and reduced disease-free and overall survival (P = 0.0067 and P = 0.0026, respectively)." (PMID 25885472, 2015). "Furthermore, high expression of AURKB is associated with poor prognosis and can predict tumor aggressiveness in HCC." (PMID 38396874, 2024). "Finally, high percentage of Aurora kinase B positive tumor cells was significantly associated with reduced disease-free and overall survival in 261 ER-positive breast cancer patients, who have received tamoxifen as first-line adjuvant endocrine treatment." (PMID 25885472, 2015). "In addition a member of the Aurora kinase family AURKA (closely associated with AURKB) involved in tumor progression has been found to be over expressed in smoking-related tumors." (PMID 22952714, 2012). "In vivo validation using xenograft models further confirmed that AURKB knockdown suppressed tumor growth, and this effect was significantly reversed by PSAT1 overexpression." (PMID 40784984, 2025). "This mirrors findings for AURKA, a close homolog of AURKB, which has been reported to facilitate tumor progression via modulation of alternative splicing." (PMID 40784984, 2025). "Let-7b-5p and AURKB expression levels in patient tumor tissue and adjacent normal tissue samples were investigated by qRT-PCR." (PMID 39787178, 2025). "Elevated AURKB expression is strongly correlated with tumor proliferation, invasion, metastasis, and drug resistance, making it a robust predictor of poor clinical outcomes." (PMID 40784984, 2025).
tumor (continued). "Overall, these findings position AURKB as a compelling candidate driver gene in CRC, robustly linked to tumor progression and unfavorable prognosis." (PMID 40784984, 2025). "Further functional assays demonstrated that the reintroduction of NPM1 partly reversed the growth arrest, apoptosis, and ferroptosis of tumor cells induced by AURKB knockdown." (PMID 39927464, 2025). "In this work, the authors identify aurora kinase B (AURKB) as a critical therapeutic target for MCC, supported by tumour shrinkage and increased survival when using the AURKB inhibitor AZD2811 nanoparticle formulation in MCC preclinical models." (PMID 39939315, 2025). "Although AURKB is known to play a key role in chromosome segregation and tumor progression, the role of AURKB in pathological retinal angiogenesis remains elusive." (PMID 41155961, 2025). "Multivariate Cox regression revealed that tumor status (with tumor, HR = 1.783, p = 0.005) and AURKB expression (high, HR = 1.561, p = 0.025) serve as independent risk factors for total survival in HCC patients." (PMID 38396874, 2024). "Previous studies have indicated that AURKB is overexpressed in various tumors and contributes to tumor development and progression." (PMID 38515112, 2024). "Second, experimental validation through in vitro and in vivo studies is necessary to confirm the functional role of AURKB in tumor progression and immune modulation." (PMID 39014265, 2024). "There was a significant difference in the AURKB expression level between tumor tissues and normal tissues (** p < 0.01; ***, p < 0.001)." (PMID 38396874, 2024). "As the results showed, we found that the growth of tumor cell xenografts was significantly suppressed in the AURKB knockdown group, concomitant with the reduction of the tumor weight." (PMID 38515112, 2024). "AURKB was identified to be obviously upregulated in the tumor compared to the normal tissues of STAD patients." (PMID 38956367, 2024). "Although AURKB is a possible target protein and prognostic biomarker for many tumor therapies, the specific role and impact of AURKB expression on HCC progression has not been determined, especially in the diagnosis and prognosis of HCC." (PMID 38396874, 2024). "Upregulation or overexpression of AURKB has been established across a variety of human tumours as a contributor to tumorigenesis." (PMID 38287178, 2024). "Aurora kinase B (AURKB) overexpression promotes tumor initiation and development by participating in the cell cycle." (PMID 38396874, 2024). "More importantly, the analysis of tumor stemness indicated that tumor patients with higher expression of AURKB corresponded to stronger stemness." (PMID 38956367, 2024). "This positions AURKB as a crucial target for studying tumor immune evasion mechanisms and developing novel immunotherapeutic strategies." (PMID 39014265, 2024). "The overexpression of AURKB genes can lead to aneuploidy, resulting in genomic instability and a higher likelihood of tumor development." (PMID 39689117, 2024). "Our findings provide important clues for further investigation of the potential role of AURKB in tumour immunity and immunotherapy." (PMID 38898693, 2024). "In vivo results consistently showed that AURKB up-regulation not only promoted tumor growth, but also promoted tumor metastasis." (PMID 37318676, 2023). "Tumor cells and patient-derived xenografts (PDXs) sensitive to AURKB and TTK inhibitors consistently showed high expression levels of BH3-interacting domain death agonist (BID), while cell lines and PDXs with low BID were uniformly resistant." (PMID 37443114, 2023).
tumor (continued). "For other tumor types, however, data about the prognostic value of AURKB are less explored and primarily rely on experimental assays using pharmacological inhibitors." (PMID 36839989, 2023). "Our data suggest that survivin phosphorylation at S20 and T117 by PLK1 and AURKB is essential for tumor progression in AA patients with TNBC and contributes to racial disparities in TNBC." (PMID 36627281, 2023). "The fate of tumor cells after SAC abrogation is driven by an AURKB/ CASP-2 signaling mechanism, regulated by BID levels." (PMID 37443114, 2023). "Recently, AURKB amplification or overexpression has been reported frequently in various malignancies, suggesting a higher tumor stage and a poor prognosis." (PMID 37079315, 2023). "Our in vitro and in vivo findings suggest that the phosphorylation of survivin by PLK1 and AURKB promotes tumor cell proliferation and cell cycle progression in AA TNBC cells but not in EA TNBC cells." (PMID 36627281, 2023). "Here, we demonstrate that BID levels regulate an AURKB/CASP-2 mitotic checkpoint that determines the fate of tumor cells when the SAC is overridden; senescence if BID expression is low but cell death in case of high BID levels." (PMID 37443114, 2023). "More importantly, treatment with a miR-4270 inhibitor not only rescued the tumor-suppressing effect of ELFN1-AS1 silencing but also abrogated the tumor suppressor functions of AURKB silencing in CC cells." (PMID 36561847, 2022). "AURKB is also a mitotic driver, is overexpressed in a variety of tumor tissues, and promotes tumor invasion." (PMID 35699421, 2022). "The most significant target genes were putative tumor oncogenes/promoters (TK1, KIF2C, UBE2C, AURKB) and potential tumor suppressors (CALCOCO1, CIRBP, KLHDC1, CBX7)." (PMID 36358602, 2022). "This signaling pathway reduces cell death by altering the expression of genes involved in the apoptotic process such as BIM, NFκB1, NFκB2, AURKA, and AURKB, thereby increasing tumor growth." (PMID 36482411, 2022). "Both AURKA and AURKB are highly expressed in HCC, and overexpression is associated with tumor aggressiveness, an unfavorable prognosis, and poorer outcomes." (PMID 35062934, 2022). "We examined an EGFR exon 19-deleted LU5221 PDX model and observed that upfront combinations with osimertinib and AURKB inhibitor AZD2811 (25 mg/kg) or sequential combination delayed tumor regrowth relative to monotherapy." (PMID 36575215, 2022). "We validated the AZD2811 AURKB combination benefit in vivo in two of three models tested, with robust delayed tumor regrowth observed in an upfront drug combination." (PMID 36575215, 2022). "The investigation of the common 68 proteins in The Human Protein Atlas database (; proteinatlas.org) revealed a similar association between tumor and normal tissues at the protein level for CKAP2L, AURKB, CDC25A, APIP, and LGALS3." (PMID 36529823, 2022). "Upregulation of AURKB is highly correlated with abscission failure, polyploidization, and tumor formation." (PMID 33510150, 2021). "Over the years it has been shown that AURKB is overexpressed in various tumors and contributes to tumor development and progression." (PMID 33915740, 2021). "AZD1152 (barasertib) has been shown to selectively inhibit AURKB and inhibit tumor growth in a dose-dependent manner in different preclinical xenograft models." (PMID 33123754, 2021). "In fact, its role in tumor cell transformation was clarified by overexpressing AURKB in murine epithelial cells." (PMID 33915740, 2021). "Hepatocellular carcinoma tissues also showed significantly elevated mRNA expression of AURKB compared to paired healthy liver tissues and was found to be an independent prognostic marker for tumor invasiveness and prognosis." (PMID 33915740, 2021). "Deregulation of cell cycle plays a critical role in tumor initiation, progression, invasion and metastasis and the proteins involved in the regulation of cell cycle including AURKB are overexpressed in various tumors." (PMID 33915740, 2021).